EPHA2 (EPH receptor A2)
Diseases named in the same sentence as EPHA2 in open-access papers (continued):
Sharing a sentence is not in itself a finding about the gene and the disease.
cancer (continued). "The receptor tyrosine kinase ephrin type-A receptor 2 (EphA2) is highly expressed in many types of human cancer but found at very low levels in most normal epithelial tissues, indicating its potential application in cancer therapy." (PMID 38279277, 2024). "A phase I study in nine advanced EphA2-positive cancers, including two CRCs, evaluated the dose escalation and biodistribution of DS-8895a, an anti-EphA2 antibody." (PMID 38651144, 2024). "EphA2 is mainly restricted to proliferating epithelial cells in adults but is also overexpressed in cancer cells." (PMID 39766211, 2024). "Herein, a computational approach is presented to investigate the relationship between Ship2-Sam/EphA2-Sam interaction and cancer onset and further progression." (PMID 38474536, 2024). "Conversely, ligand-independent overexpression of EphA2 promotes cancer cell migration through AKT-induced serine phosphorylation." (PMID 38811954, 2024). "As a promising target in cancer, EphA2 has been studied in certain cancers, but research on EphA2 in OSCC is limited." (PMID 38916835, 2024). "EphA2 is known to regulate the PI3K-AKT signaling pathway in many cancer types, which prompted us to examine phosphorylated AKT." (PMID 38279277, 2024). "Our original results showed that silencing EphA2 was associated with reduced activation of ERK1/2, SRC, and AKT, which are key pathways involved in cancer cell survival and proliferation." (PMID 39056783, 2024). "Although many previous studies have reported the expression of EphA2 in harvested cancer tissues, it is released from the cell surface by enzymes and detected as soluble EphA2 in the serum." (PMID 39766211, 2024). "From the functional standpoint, c-Cbl-mediated ubiquitination of EphA2 represents a crucial oncosuppression mechanism in cancer cells." (PMID 39596256, 2024). "This study underscores the potential of EphA2-targeted immunotoxins in selective cancer treatment, with the orientation of the antibody–toxin linkage playing a critical role in therapeutic efficacy." (PMID 39685591, 2024). "For instance, ligand-independent serine phosphorylation of EphA2 stimulates migration, invasion, and cancer progression, particularly when ligand-induced forward signaling is decreased." (PMID 38811954, 2024). "CLDN1 was demonstrated to cause chemoresistance in CRC via upregulating ephrin type-A receptor 2 (EPHA2) tyrosine kinase, which enhances downstream the AKT signaling pathway, and CD44 expression, which promotes cancer stemness and chemoresistance." (PMID 38731853, 2024). "EphA2 represents an important antigen that can be used for immunotherapy-based strategies, as EphA2 immunotherapy represents a promising frontier in cancer treatment, with ongoing research aimed at optimizing efficacy and safety." (PMID 39596256, 2024). "Numerous preclinical studies have focused on EphA2 as a promising therapeutic target in cancer, particularly in CRC." (PMID 39525153, 2024). "Two phase I trials were conducted in patients with advanced or metastatic EphA2-positive cancers to test safety, tolerability, pharmacokinetics, pharmacodynamics, and biodistribution of the anti-EphA2 mAb DS-8895a." (PMID 39596256, 2024). "Multiple Eph receptor tyrosine kinases, particularly EphA2, are overexpressed in various cancers and mediate pro-oncogenic signaling mechanisms in cancer cells." (PMID 39056783, 2024). "In cancer cells, EphA2 action is the result of a delicate balance between oncosuppressive and oncogenic signals, which depend on the availability of cognate ephrin ligands." (PMID 39596256, 2024). "Senescent cells were shown to secrete EphA2-expressing EVs which promote cancer cells’ proliferation by binding to ephrin-A1 and inducing reverse signaling." (PMID 38534339, 2024). "Our review highlights IL-13Rα2 and EphA2 as clinically relevant biomarkers for these cancer subtypes, noting their minimal expression in normal tissue, which underscores their potential as targets for CAR T-cell therapy." (PMID 38612592, 2024).
cancer (continued). "As such, EphA2 is pivotal for intercellular communication, influencing both normal physiological processes and pathological conditions, including cancer." (PMID 38612592, 2024). "While EphA2 is overexpressed in many types of cancer, canonical phosphorylation of EphA2 is often reduced due to insufficient cell-cell contact or due to decreased expression of the ephrin-A1 ligand." (PMID 39466050, 2024). "This section will highlight data supporting major molecular mechanisms driven by EphA2 in cancer as well as the impact on cancer hallmarks that should be considered for effective anti-EphA2 therapy." (PMID 39596256, 2024). "Examining EphA2 in more detail, its phosphorylated tyrosine kinase activity inhibits the chemotactic migration of cancer cells." (PMID 38811954, 2024). "Pro-oncogenic effects of EphA2 in cancer cells are mainly orchestrated through ligand-independent activation of EphA2, and the presence of exogenous ephrinA1 induces EphA2 internalization and degradation and reduces its oncogenic signaling." (PMID 39056783, 2024). "At present, several EphA2-targeted therapeutics are being evaluated in clinical trials in various cancers in which EphA2 has an established oncogenic function." (PMID 36835335, 2023). "The different levels of EphA2 in normal cells compared with cancer cells signifies its relevance as a therapeutic target." (PMID 37530973, 2023). "Some other proteins of interest include the surface protein FN1 and the enzyme butyrylcholinesterase (BCHE), both being known as unfavorable prognostic markers for different cancers along with EphA2." (PMID 37637064, 2023). "EphA2 activation by its canonical ligand, ephrin-A1, evokes EphA2 canonical signaling inhibiting cancer cell migration and invasion." (PMID 36980592, 2023). "These differential ADAM17-regulated levels of EphA2 pS897 directly correlated with ADAM17-dependent cancer cell migration." (PMID 36998455, 2023). "These were achieved by conjugating the devices with an EphA2-specific monoclonal antibody that have been shown to selectively bind to EphA2-overexpressing cancer cells." (PMID 37530973, 2023). "Although accumulated evidence supports the targeted treatment of EphA2 for cancer therapy, challenges remain." (PMID 37063424, 2023). "Through this work, we showed a differential response to TrkA/EphA2 axis inhibitors depending on the nature of the extracellular matrix in which the cancer cells were cultured." (PMID 38072918, 2023). "The present results clarified the relationship between the p38-MK2 axis and EphA2 non-canonical activation and provide an effective strategy for anti-EphA2 therapy to prevent the malignant progression of human cancers." (PMID 37059179, 2023). "EphA2 has been shown to be highly expressed in many cancers and has been shown to regulate the PI3K-AKT signaling pathway." (PMID 36835335, 2023). "Although EphA2 was first studied in the context of neuronal migration during embryogenesis, it has since been shown to regulate cancer cell growth, migration, invasion, and angiogenesis." (PMID 36835335, 2023). "Ligand-independent Ser897 phosphorylation of EphA2 stimulates migration/invasion and cancer progression, which is dependent on a decreased level of ligand-induced forward signalling." (PMID 36830852, 2023). "EphA2 and ephrin-A1 increase was also more prevalent in the initial phase of cancer development as compared to the later phase, and ephrin-A1 overexpression promoted the proliferation of HT29 colorectal cancer cells." (PMID 36830852, 2023). "Higher expression of EphA2 is observed in malignant cancer-derived cell lines and advanced forms of cancer." (PMID 37530973, 2023). "Cancer cell migration in dependence of IR, EphA2, and paracrine signaling mediated by ADAM17 was determined using transwell migration assays." (PMID 36998455, 2023). "EPHA2 expression and its correlation with cancer progression and metastasis in CRC tissue were also demonstrated." (PMID 36890818, 2023).
cancer (continued). "In comparison to its ligand, EphA2 is often overexpressed in various cancer types, in particular non-small cell lung cancer (NSCLC), where it is associated with poor prognosis." (PMID 36998455, 2023). "EphA2 highly expressed in a variety of human cancers, playing roles in proliferation, migration, and invasion." (PMID 37063424, 2023). "For example, in the presence of ephrinA1, EphA2 is dephosphorylated at S897 leading to inhibition of cancer cell motility and invasion." (PMID 36471440, 2022). "The function of EPHA2 in cancer is complex and the EPHA2-mediated signaling system is always dysregulated in many tumors." (PMID 35673569, 2022). "Increased expression of EphA2 is correlated with cancer progression, metastatic spread, and patient survival, and overexpression of EphA2 has been shown to specifically increase migration, invasion, metastasis, and angiogenesis." (PMID 35668076, 2022). "Our work highlights the critical functional role of exosomal EPHA2 in promoting angiogenesis via mediating the communication between tumorigenic cancer cells and microenvironmental endothelial cells." (PMID 35673569, 2022). "Ligand activation of EPHA2 or EPHA2 knockdown by small interfering RNA inhibited EGF-induced cell motility of EGFR-overexpressing human cancer cells, indicating a functional role of EPHA2 in EGFR-expressing cancer cells." (PMID 36297233, 2022). "Erythropoietin-producing hepatocellular receptor-2 (EphA2) is a member of the Eph receptor kinase family, which is overexpressed frequently in diverse cancer types." (PMID 36132127, 2022). "EphA2 is also an interesting protein related to cancer metastasis, which is overexpressed in various cancer cells such as melanomas, ovarian, prostate, lung, and breast cancers." (PMID 35890274, 2022). "Cell imaging was conducted by CLSM imaging after incubation with human prostate PC-3 cancer cells that were first stained with anti-EPhA2 monoclonal antibody and fluorescent secondary antibody." (PMID 35745035, 2022). "To search for the downstream molecular mechanism of the cancer-promoting effect of EphA2, we carefully analyzed the meaningful differentially expressed genes in the sequencing results." (PMID 36478746, 2022). "We looked for conditions in which the interaction between EGFR and EphA2 was increased in cancer cells and analyzed the binding site between the two receptors as a way to identify a functional role." (PMID 35668076, 2022). "Compared to the folate conjugate core-shell NPs developed earlier by our group, we observed nearly 25 times higher NP internalization into A549 cancer cells when conjugating antibodies against EphA2 onto the NP surfaces." (PMID 35893781, 2022). "In most cancer cells, the tyrosine kinase Eph receptor A2 (EphA2) is overexpressed and plays a crucial part in deteriorating into cancer malignancy." (PMID 35745035, 2022). "ALW-II-41-27 was first identified in 2009, which decreased the phosphorylation of EPHA2 at Ser897 in many cancers." (PMID 36297233, 2022). "Among TAAs, BIRC5 and EphA2 are prognostic markers and therapeutic targets in various cancers, including GBM." (PMID 36439089, 2022). "The shedding of EphA2 by MT1-MMP was also found to play other important roles in cancer progression." (PMID 36132127, 2022). "For example, EphA2 in cancer cells has been silenced through small interfering RNAs (siRNAs), representing intriguing tools for gene knockdown." (PMID 36142306, 2022). "Due to the correlation of aggressive pathological and clinical characteristics in human cancers and EphA2 upregulation, many studies have been focused on the possibility to treat cancer through EphA2 downregulation." (PMID 36142306, 2022). "In recent years, the role of EphA2 in the occurrence and development of cancer has become a research hotspot and is considered a promising potential target." (PMID 36478746, 2022).
cancer (continued). "This study shed the light on the advantage of co-targeting CAFs and cancer cells since the authors demonstrated that combining mhFAP CAR-T cells with EphA2 CAR-T cells increased overall antitumor activity." (PMID 35211124, 2022). "EphA2 activation by its natural ligand ephrinA1 (canonical signaling) regulates cellular repulsion and adhesion, but the role of EphA2 in cancer is more complex with data suggesting either pro- or anti-oncogenic functions." (PMID 36471440, 2022). "EphA2 has been considered as a key driver of VM process in various types of cancers, including PCa34." (PMID 36418859, 2022). "Activation of K-Ras activates AKT, which then phosphorylates Ser897 of EphA2 and results in increased cancer proliferation." (PMID 35668076, 2022). "We therefore combined PHLDA1, DUSP4, and EPHA2 genes into an optimized signature henceforth referred to as “Carcinoma of the Ovary MEK/ERK Signature” (COMS)." (PMID 36362153, 2022). "MM-310, a liposomal formulation of a docetaxel prodrug using EphA2 as drug delivery target on cancer cells, has been tested in patients with solid tumors but results are not yet available (NCT03076372)." (PMID 34440844, 2021). "eHSP90 binding to LRP1 activates ERK, AKT, and NF-κB pathways and induces ephrin type-A receptor 2 (EPHA2) recruitment and activation, promoting lamellipodia formation and cancer cell motility and invasion." (PMID 34722515, 2021). "As a RTK on the cell membrane, EphA2 can regulate many oncological behaviors of cancer cells through different signaling pathways." (PMID 33941853, 2021). "One of our findings is that exosomal EphA2 confers the invasive phenotype transfer from drug-resistant cells to drug-sensitive cancer cells." (PMID 33879771, 2021). "Colocalization of EGFR with EphA2 in cancer cells was shown together with modulation of adhesion-induced EphA2 expression by activated EGFR." (PMID 33572284, 2021). "Recently, ephrin receptor A2 (EPHA2) was proposed as the epithelial cell receptor on human cancer cell lines." (PMID 33596248, 2021). "Accumulating evidence suggests that EphA2 is overexpressed in various cancers, including colorectal cancer, breast cancers, GC, and nasopharyngeal carcinoma." (PMID 33941853, 2021). "For RTKs, EGFR, MET and EPHA2 were phosphorylated in almost all cell lines, highlighting a pattern of multiple cancer pathway activation." (PMID 33750427, 2021). "Our current data suggested a correlation between the inhibition of cell migration and reduced SOD3-driven phosphorylation of EphA2, which promoted cancer cell migration, but the exact mechanism explaining SOD3 function in cell migration remains elusive." (PMID 33919252, 2021). "Next, to investigate and compare the expression of known vascular cell markers we examined the gene expression of VE-cadherin and Ephrin type-A receptor 2 (EphA2) in the ECs and VM-competent cancer cells (breast and pancreatic)." (PMID 34552183, 2021). "EphA2 is overexpressed in many cancers such as prostate, ovarian, breast, lung, brain, urothelial, and skin." (PMID 33685469, 2021). "MTT and cell cycle assays demonstrated that deletion of EphA2-SE suppressed cancer cell proliferation by blocking PI3K/AKT and WNT/β-catenin signaling pathway." (PMID 33712565, 2021). "A proposed mechanism through which LMWPTP promotes cancer is through dephosphorylation of an RTK called EphA2 at its tyrosine 772 residue." (PMID 34884670, 2021). "Recent reports demonstrated the importance of EPHA2 expression for EBV infection in conventional cancer cell lines." (PMID 33596248, 2021). "They accomplish their action by forming ternary protein complexes with additional molecules, which can include EphA2 in the context of cancer." (PMID 35096972, 2021). "EphA2 is overexpressed in different cancers including breast, endometrial, lung, ovarian, pancreatic and prostate, and its expression is always associated with adverse outcomes." (PMID 34863235, 2021).
cancer (continued). "LMW-PTP, overexpressed in many cancers, has overlapping functions with EphA2, including cell motility and resistance to therapy." (PMID 33572284, 2021). "EphA2, as a key member of the RTKs, controls multiple physiological and pathological processes and is one of the promising targets for the treatment of cancers including GC." (PMID 33941853, 2021). "In cancer cells, EphA2 tyrosine phosphorylation is often low, consistent with the unusual effects of EphA2 canonical signaling, which inhibits major oncogenic networks such as RAS-ERK and AKT-mTORC12,20,21." (PMID 34857764, 2021). "By screening multiple cancer cell lines in which EphA2 is known to be phosphorylated on S89727,29, we confirmed phosphorylation on two other residues in the linker, S892 and S901." (PMID 34857764, 2021). "In detail, EGFR, in multiple cancer settings, stimulated the phosphorylation of unliganded EphA2 via AKT and p90RSK at S897." (PMID 33572284, 2021). "This review consolidates the available literature of the role of the Eph receptor family, and particularly EphA2, in tumorigenesis, with the aim to develop a better understanding of Eph signalling pathways for potential targeting in novel cancer therapies." (PMID 33430066, 2021). "While there was no clear pattern of differential expression between normal and cancer organoids for EPHA2 at the RNA and protein level, the subcellular location of the protein differed markedly." (PMID 33596248, 2021). "In summary, our results indicated the key function of exosomal EphA2 involved in the crosstalk between drug resistance and cancer progression." (PMID 33879771, 2021). "Ephrin type A receptor 2 (EphA2) is a receptor tyrosine kinase that has been found to be overexpressed in a variety of cancers, including HCC." (PMID 34445353, 2021). "In keeping with the potential for EphA2 to impinge on cancer cell stemness features, several observations point to a role for EphA2 in promoting survival and functions of those cell subpopulations." (PMID 33572284, 2021). "A total of 394 common DEGs with the same direction were obtained, and EphA2 expression was found to be significantly decreased in the three cancer cell lines." (PMID 33712565, 2021). "Although numerous studies have demonstrated that ligand-independent S897 phosphorylation of EphA2 (pS897-EphA2) promotes cancer development and progression, the role of ligand-independent Y772 phosphorylation of EphA2 (pY772-EphA2) in cancers is unclear." (PMID 32848131, 2020). "VE-cadherin and EphA2 are overexpressed in aggressive cancer cells and play key roles in the formation of matrix-rich vessel-like networks called VM." (PMID 31936664, 2020). "EphA2 overexpression contributes to ErK-1/2 activation and cancer progression has been reported in many types of cancers." (PMID 32848131, 2020). "Increased LMW-PTP expression functions to reduce EphA2 phosphotyrosine content, contributing to elevated EphA2 levels in cancer cells." (PMID 32811512, 2020). "Ephrin type-A receptor 2 (EphA2) is frequently overexpressed in different types of cancer and has been reported to impinge on multiple signaling pathways, including PI3K, Akt and MAPK." (PMID 32756339, 2020). "Ephrin A1’s expression pattern in cancer seems to differ from that of EphA2, with attenuation in a variety of aggressive tumors, particularly those overexpressing EphA2." (PMID 32811512, 2020). "EPH Receptor A2 (EphA2) is a tyrosine kinase capable of activating multiple diverse signaling pathways involved in tissue homeostasis and cancer and described as being a functional CSC marker in GB." (PMID 33101285, 2020). "It is considered that deficient cell-to-cell contact (commonly found in malignant cells) and insufficient levels of ephrin A1 on cancer cells reduce EphA2 phosphorylation." (PMID 32811512, 2020). "For instance, DS-8895a, an anti-EphA2 mAb, inhibits the phosphorylation of EphA2 in cancer cell lines exposed to ephrin-A1." (PMID 32629797, 2020).